CGB3 (chorionic gonadotropin subunit beta 3)
Description:
Beta subunit of the human chorionic gonadotropin (hCG). hCG is a complex glycoprotein composed of two glycosylated subunits alpha and beta which are non-covalently associated. The alpha subunit is identical to those in the pituitary gonadotropin hormones (LH, FSH and TSH). The beta subunits are distinct in each of the hormones and confer receptor and biological specificity. Has an essential role in pregnancy and maternal adaptation. Stimulates the ovaries to synthesize the steroids that are essential for the maintenance of pregnancy.
Synonyms: CG-beta; CGB
Tractability: Small molecule: a structure with a bound ligand is known. Antibody: UniProt places it where antibodies can reach, with high confidence; its Gene Ontology location is reachable by antibodies, with high confidence; UniProt predicts a signal peptide or a membrane-spanning region.
Gene: Protein-coding gene on chromosome 19 (49,022,869 to 49,024,333, reverse strand). Ensembl gene ENSG00000104827.
Subcellular location: Secreted
Pathways (Reactome):
Gene expression (Transcription): TFAP2 (AP-2) family regulates transcription of growth factors and their receptors
Metabolism of proteins: Glycoprotein hormones
Gene Ontology:
Molecular function: protein binding; hormone activity
Biological process: apoptotic process; cell-cell signaling; female gamete generation; G protein-coupled receptor signaling pathway; hormone-mediated signaling pathway; signal transduction; cell communication; signaling
Cellular component: extracellular region; pituitary gonadotropin complex
Genetic constraint (gnomAD): Loss-of-function variants: 3 observed, 2.42 expected, observed/expected ratio (o/e) 1.24, 90% interval 0.5 to 1.9. That is too few expected variants to judge how well the gene tolerates losing a copy. Missense variants: 31 observed, 67.16 expected, observed/expected ratio (o/e) 0.46, 90% interval 0.35 to 0.62. Synonymous variants: 11 observed, 22.95 expected, observed/expected ratio (o/e) 0.48, 90% interval 0.3 to 0.79.
Homologues: Orthologues: macaque CGB8 (80% identical), Drosophila melanogaster Gpb5 (16% identical). Paralogues in human: CGB5 (100% identical), CGB8 (100% identical), CGB7 (98% identical), CGB2 (97% identical), CGB1 (92% identical), LHB (70% identical), TSHB (30% identical), FSHB (26% identical), GPHB5 (22% identical).
Diseases named in the same sentence as CGB3 in open-access papers:
CGB3 is named in the same sentence as 8 diseases in open-access papers, as found by Europe PMC text mining. Sharing a sentence is not in itself a finding about the gene and the disease. The quoted sentences say what the papers report.
breast carcinoma (2 papers, 2017 to 2024). "The β-HCG genes CGB3, CGB5, CGB8 and CGB9, called type II β-HCG genes, were found to be expressed in 46% of breast cancer cases, but not in normal mammary epithelium." (PMID 28754015, 2017).
cervical cancer (1 paper, 2022). A primary or metastatic malignant neoplasm involving the cervix. "Furthermore, CGB3 also acts as a tumor suppressor in cervical cancer." (PMID 36686788, 2022).
COVID-19 (1 paper, 2024). A disease caused by infection with severe acute respiratory syndrome coronavirus 2. "Expression levels of chorionic hormone synthesis genes such as CGB3 and EVT invasion- and differentiation-related genes such as IGFBP3 and EGFR in the second-trimester COVID-19 group were also consistent with those in the second-trimester control group." (PMID 38441496, 2024).
rhabdoid tumor (1 paper, 2022). An aggressive malignant embryonal neoplasm usually occurring during childhood. "Although the chorionic gonadotropin subunit beta 3 (CGB3) gene is overexpressed in fetal cells and various cancer types, the connection between CGB3 and rhabdoid tumors has yet to be investigated." (PMID 35954348, 2022).
urothelial carcinoma (1 paper, 2025). A malignant neoplasm derived from the transitional epithelium of the urinary tract (urinary bladder, ureter, urethra, or renal pelvis). "We first wondered how frequently CGB7 is coexpressed with CGB3, CGB5, CGB8, and CGA in urothelial carcinoma." (PMID 40501795, 2025). "Further evaluation of expression of these genes in the TCGA urothelial carcinoma cohort revealed that while tumors tend to co-express CGB3, CGB5, and CGB8, CGB7-expressing tumors cluster independently, suggesting that CGB7 is less frequently co-expressed with CGB3, CGB5, and CGB8." (PMID 40501795, 2025).
cancer (4 papers, 2019 to 2025). A tumor composed of atypical neoplastic, often pleomorphic cells that invade other tissues. "Analysis of mRNA derived from placentas and cancer tissues pointed to a twenty fold higher transcriptional activity of CGB5 compared to CGB3 or CGB8." (PMID 31362717, 2019). "The expression of CGB3–9 genes was not only confirmed for all studied samples, but was also shown to be significantly higher in cancer than control ovarian tissue." (PMID 31362717, 2019). "Numerous studies have demonstrated that beta-hCG-encoding genes are expressed in various cancers, but expression of these genes (CGB3, CGB5, CGB7, and CGB8) across diverse cancers has not been systematically evaluated." (PMID 40501795, 2025). "We sought to systematically evaluate the expression patterns of each functional CGB gene (CGB3, CGB5, CGB7, and CGB8) across 20 distinct cancer types utilizing gene expression data from The Cancer Genome Atlas (TCGA)." (PMID 40501795, 2025).
tumor (3 papers, 2022 to 2025). "We first tested whether the associations between CGB7 and CD8+ T cell infiltration and tumor subtype are upheld independently of CGB3, CGB5, and CGB8 expression." (PMID 40501795, 2025). "ALKHB5, SLC7A2, and CGB3 showed a similar tendency to inhibit tumor development, suggesting that SLC7A2 and CGB3 may also play a suppressor role in GC; the internal mechanism of how ALKBH5 regulates these genes needs to be further explored." (PMID 36686788, 2022).
CGB3 also shares sentences with these, for which no sentence is quoted: bladder cancers (1 paper).